LRP1 (LDL receptor related protein 1)
Diseases named in the same sentence as LRP1 in open-access papers (continued):
Sharing a sentence is not in itself a finding about the gene and the disease.
Hyperglycemia (10 papers, 2010 to 2025). An increased concentration of glucose in the blood. "Animal studies have demonstrated that hyperglycemia suppresses LRP1 expression and that its deficiency in neurons leads to the impairment of insulin signaling pathways and glucose uptake." (PMID 33013281, 2020). "Further studies are warranted to elucidate whether LRP1 mediates cognitive decline caused by hyperglycemia, and the association between the LRP1 rs1799986 polymorphism and MCI in T2DM should be validated in future large population studies." (PMID 33013281, 2020). "Based on our observations in hOC-GFP transgenic mice, the regulation of human Ocn promoter-driven GFP expression by hyperglycemia and LRP1 depletion is similar as that of mouse OCN." (PMID 34489478, 2021). "Further studies with large cohorts should be designed to elucidate the roles of LRP1 in hyperglycemia-induced cognitive decline." (PMID 33013281, 2020). "Insulin use and increased HbA1c level often indicate poor glucose control and hyperglycemia downregulates LRP1 expression in the brain." (PMID 33013281, 2020). "Indeed, failure of compensatory proliferation of β-cells leads to hyperglycemia and insulin dependence in T2D patients, and ablation of LRP1 in β-cells from mice fed a high fat-diet impairs β-cell function and proliferation." (PMID 39596044, 2024). "An animal study has found that hyperglycemia suppressed LRP1 expression." (PMID 33013281, 2020). "Hyperglycemia may downregulate LRP1 expression, which leads to a vicious cycle which decreased the translocation of GLUT4 to the plasma membrane." (PMID 32908938, 2020). "In fact, it has been documented that insulin insufficiency and hyperglycemia may alter LDL Receptor Related Protein 1(LRP1) function, thus decreasing Aβ clearance by modulating tight junction proteins, endothelial cells, and the remodeling of extracellular matrices." (PMID 39992249, 2025). "For example, reduced expression of LRP1 in the liver was observed in diabetic OLETF rats, and an in vitro model of hyperglycemia (25 mM glucose in culture medium) suppressed LRP1 expression in HepG2 cells." (PMID 39456746, 2024). "The results showed OCN AAV-shRNA-injected LRP1 eKO mice displayed severe hyperglycemia, displaying a reverse response to the normalized non-fasting glucose level in LRP1 eKO mice following STZ injection." (PMID 34489478, 2021).
myocardial infarction (10 papers, 2016 to 2025). Gross necrosis of the myocardium, as a result of interruption of the blood supply to the area, as in coronary thrombosis. "Increased PDGF signaling via SMC Pdgfrb in Lrp1-KO mice increased aortic atherosclerosis, and loss-of-function PDGFD variants are associated with a reduced risk of myocardial infarction." (PMID 39531316, 2024). "The binding of SP16 to LRP-1 in mouse model with myocardial infarction and in a mouse model with lung pneumonia, resulted in an anti-inflammatory and pro-survival action." (PMID 36831299, 2023). "In this way, it has been proposed LRP1 agonist ligands to provide cardioprotection during ischemia–reperfusion after acute myocardial infarction." (PMID 34203120, 2021). "Data from animal models as well as a pilot study of humans with acute myocardial infarction support the role of LRP1 as a potential treatment for ischemia-reperfusion injury." (PMID 33956804, 2021). "LRP1 gene expression is also increased in blood mononuclear cells from patients with myocardial infarction." (PMID 27430968, 2016). "During myocardial infarction, ECM1 produced by macrophages and pericytes/vascular cells, binds to the fibroblast surface receptor LRP1, promoting fibrosis." (PMID 39910700, 2025).
tauopathies (10 papers, 2020 to 2025). "The downregulation of LRP1 reduces Tau uptake and transneuronal spread of the pathology, suggesting that LRP1 is a potential target for tauopathy." (PMID 38971320, 2024). "Understanding the individual pathways of each molecule and how they interconnect to LRP1 is key to the development of potential therapeutic intervention in AD and potentially other tauopathies." (PMID 33930462, 2021). "Rauch and colleagues provide new insight into tau physiology and potential therapeutic targets for tauopathies: LRP1; the associated lysine residues within the MTBR; and the yet unstudied processes downstream of this LRP1-tau interaction." (PMID 33424736, 2020). "Given that many tauopathies have significant glial pathology, the effect of LRP1 on BBB clearance and transmission of tau in other cells types must be investigated." (PMID 33424736, 2020). "The distribution of LRP1 in vulnerable brain regions in specific tauopathies would be of great interest in this respect." (PMID 33424736, 2020). "LRP1, often downregulated in tauopathies, regulates tau clearance and endo‐lysosomal trafficking." (PMID 41399158, 2025). "If LRP1 binds and transmits specific tau conformations differently, these findings may have greater relevance for specific tauopathies where post-translation modifications or other factors impact conformation." (PMID 33424736, 2020). "Multiple factors including APOE isoforms, tau conformational strains and the epichaperone system might therefore modulate tau transmission via LRP1, partially explaining the diverse neuropathologies and clinical syndromes found in different tauopathies." (PMID 33424736, 2020). "LRP1, as a major receptor of tau species and ApoE, may play an intermediate role between ApoE and tau species, which could point to a therapeutic potential for treating tauopathies via LRP1 interaction." (PMID 33672982, 2021). "Knockdown of LRP1 was recently shown to block the uptake of monomeric and oligomeric tau in a human neuroglioma cell line, and partially inhibit uptake of sonicated tau fibrils, warranting further investigation into how astrocytic LRP1 may mediate tau uptake and spread in tauopathies." (PMID 33071951, 2020). "The involvement of LRRK2 and LRP1 in both tau and synuclein uptake by human neurons addresses questions about the role of LRRK2 in tauopathies and the mechanistic links between the pathogenesis of PD and AD and other tauopathies, while opening some new ones." (PMID 40790356, 2025). "The vicious circle generated by activated microglia and damaged neurons based on critical molecules, including LRP1, TREM2, and PQBP1, would definitely contribute to AD and tauopathy pathologies and would be critical therapeutic targets." (PMID 34782623, 2021). "Furthermore, knockdown of LRP1 in neurons dramatically suppresses tau spread across the brain in the mouse unilaterally injected with AAV expressing human tau with P301L mutant in hippocampus, suggesting that LRP1 may represent a novel therapeutic target for tauopathies." (PMID 33996814, 2021).
colon carcinoma (9 papers, 2011 to 2024). "In colon cancer, the low expression of LRP1 in tumor cells was strongly associated with right tumor location, poor differentiation, BRAF mutation, MSI-H and CIMP-H status in our cohort as well as in an independent CRC cohort." (PMID 29507659, 2018). "Loss of LRP1 expression is associated with worse colon cancer outcomes." (PMID 29507659, 2018). "We analyzed the changes in SLC7A7 and gene mutations, acquisitions, and deletions in colon cancer, the difference in APC, TTN, KRAS, SYNE1, RYR2, and LRP1 mutations was statistically significant." (PMID 39730571, 2024). "We then demonstrated that LRP-1 and DDR1 are tightly associated in the same biomolecular complexes at the plasma membrane of colon carcinoma to constitute a new endocytosis complex." (PMID 32582700, 2020). "The LRP-1 mediated endocytosis of DDR1 supports colon carcinoma cell proliferation by promoting the entry of cell cycle to the S phase and decreasing apoptosis." (PMID 32582700, 2020). "In the present study conducted using relevant 3D collagen matrices, we showed in a surprising way that LRP-1 inhibition decreased colon carcinoma cell proliferation." (PMID 32582700, 2020). "The findings of this study have highlighted the first ever molecular association between LRP-1 and DDR1 in colon carcinoma." (PMID 32582700, 2020). "We found that LRP-1 established tight molecular connections with DDR1 at the plasma membrane in colon cancer cells." (PMID 32582700, 2020). "LRP-1B, a member of LDL-R family highly homologous to LRP-1, is downregulated in the colon cancer tissues and inhibits the growth, migration and metastasis of colon cancer cells." (PMID 32582700, 2020). "Taken together, these data indicate that LRP-1 sustains colon cancer cell proliferation, and that this process occurs only in a 3D collagen environment." (PMID 32582700, 2020). "In this report, we made several important and previously unrecognized findings regarding the role of LRP1 in colon cancer." (PMID 29507659, 2018). "To further expand our knowledge on the relevance of considering LRP1 expression in colon cancer, we analyzed LRP1 expression level and distribution in a series of 307 colon cancers with follow-up data." (PMID 29507659, 2018). "Our study showed decreased expression of LRP1 in cell lines derived from non-small lung, prostate and colon carcinoma, all consistent with results described in literature." (PMID 28662213, 2017). "Not surprisingly, eHsp90 partners with its immunomodulatory receptor LRP1 to drive cell motility in a number of cancers, as shown in colon cancer." (PMID 24805867, 2014). "The LRP1 is a multifunctional receptor that is expressed in a wide range of tissues, as well as in multiple malignancies, including colon cancer, renal cancer, and melanocytic tumours." (PMID 22027709, 2011). "In this study, we identified a new molecular way that controls the cell-surface expression of DDR1 and consequently the colon carcinoma cell proliferation and apoptosis and highlighted an additional mechanism by which LRP-1 carries out its sensor activity of the tumor microenvironment." (PMID 32582700, 2020). "Indeed, we showed that the endocytic receptor LRP-1 established tight molecular connections with DDR1 at the plasma membrane of colon cancer cells." (PMID 32582700, 2020). "Interestingly, our findings stressed that LRP-1 displays a pro-proliferative effect on colon cancer cells only in 3D type I collagen matrices." (PMID 32582700, 2020). "Third, low LRP1 IHC score in tumor cells was associated with poor OS in non-metastatic colon cancer patients, and was an important prognostic and predictive factor in metastatic patients." (PMID 29507659, 2018). "LRP1 may also partner with the inflammatory mediator NF-kB to elicit eHsp90-mediated colon cancer cell motility, while NF-kB was shown to exert pro-motility effects via TLR4 in GBM." (PMID 24805867, 2014).
colon carcinoma (continued). "Thus, miR-205 could regulate LRP1 expression in colon cancer but its precise role needs to be furher clarified." (PMID 29507659, 2018). "Reverse immunoprecipitation experiments with anti-DDR1 were also performed using the same cell lysates and confirmed that LRP-1 and DDR1 were detected in the same molecular complexes in colon carcinomas." (PMID 32582700, 2020). "Here, we addressed whether it could exist functional interplays between LRP-1 and DDR1 to control colon carcinoma cell behavior in three-dimensional (3D) collagen matrices." (PMID 32582700, 2020). "To further characterize the role of LRP-1 in the regulation of cancer cell proliferation, we investigated whether RAP treatment affects the cell cycle of HT-29 colon carcinomas." (PMID 32582700, 2020). "As its role in colon cancer has not yet been characterized, we here investigate the relationship between LRP1 and outcome." (PMID 29507659, 2018). "LRP1 expression was decreased in cell lines derived from non-small lung, prostate, and colon carcinoma as described in literature." (PMID 28662213, 2017). "Considering that LRP-1 induced HT29 cell proliferation in 3D collagen matrices and drives endocytosis of DDR1, we assume that the cell-surface expression level of DDR1 may constitute a key parameter to control growth and survival of colon cancer cells." (PMID 32582700, 2020).
esophageal squamous cell carcinoma (9 papers, 2016 to 2025). Esophageal squamous cell carcinoma (ESCC) is a type of esophageal carcinoma (EC) that can affect any part of the esophagus, but is usually located in the upper or middle third. "LRP1 enhances ESCC cell migration and invasion in esophageal squamous cell carcinoma (ESCC) through interaction with CAF-derived PAI-1 and is eventually linked with a poor prognosis in ESCC patients." (PMID 37124542, 2023). "The authors show that plasminogen activator inhibitor-1 (PAI-1) derived from cancer-associated fibroblasts promotes the invasion of esophageal squamous cell carcinoma (ESCC) cells and the migration of macrophages via lipoprotein receptor-related protein 1 (LRP1)." (PMID 33311557, 2021). "In esophageal squamous cell carcinoma, CAF-like cells produce plasminogen activator inhibitor-1 (PAI-1), which augments migration and invasion through the PAI-1/low-density lipoprotein receptor-related protein 1 (LRP1) axis via Akt-Erk1/2 pathways." (PMID 40313969, 2025). "In esophageal squamous cell carcinoma, plasminogen activator inhibitor-1 (PAI-1) derived from CAF-like cells enhances migration and invasion abilities through the Akt-Erk1/2 signaling pathways via the PAI-1/low-density lipoprotein receptor-related protein 1 (LRP1) axis." (PMID 38602594, 2024).
Hypertension (9 papers, 2012 to 2025). The presence of chronic increased pressure in the systemic arterial system. "Studies have shown that cardiovascular risk factors such as hypertension and hyperlipidemia can also induce upregulation of LRP1 to varying degrees, jointly leading to overexpression of LRP1 in advanced atherosclerotic plaques." (PMID 40083817, 2025). "LRPAP1, involved in the suitable localization and folding of LDL receptor-related protein (LRP1), has known associations with hypertension and angiogenesis, a potential avenue for hypertension treatment." (PMID 38836231, 2024). "Subjects with LRP1 rs11613352 (C>T) minor genotype TT had significantly more hypertension than those with the C allele." (PMID 29989339, 2018). "LRP1 has been proposed to have a direct effect at the artery wall (Strickland, Au, Cunfer, & Muratoglu, 2014), which might imply an association with hypertension." (PMID 29989339, 2018). "Sendra J, Llorente-Cortés V, Costales P, Huesca-Gómez C, Badimon L. Angiotensin II upregulates LDL receptor-related protein (LRP1) expression in the vascular wall: a new pro-atherogenic mechanism of hypertension." (PMID 33566965, 2021). "In conclusion, the LRP1 rs11613352 (C>T) minor genotype TT previously associated with a profile of lower TG and higher HDL‐C was associated with hypertension in men." (PMID 29989339, 2018). "We investigated the role of LRP1 rs11613352 with hypertension in a Finnish population." (PMID 29989339, 2018).
osteosarcoma (9 papers, 2011 to 2024). A usually aggressive malignant bone-forming mesenchymal neoplasm, predominantly affecting adolescents and young adults. "Through transcriptome sequencing, we previously identified a new osteosarcoma-specific, frequent fusion gene, LRP1–SNRNP25, and found that it played an important role in tumor cell invasion and migration." (PMID 38678020, 2024). "To explore the molecular mechanism of the LRP1–SNRNP25 fusion in affecting osteosarcoma cell migration and invasion, we evaluated the migration and invasion-related molecular signaling pathways by western blotting." (PMID 38678020, 2024). "On the other hand, osteosarcoma cells overexpressing LRP1–SNRNP25 were more likely to undergo lung and liver metastasis." (PMID 38678020, 2024). "We extracted genomic DNA from LRP1–SNRNP25-positive osteosarcoma samples, subjected the samples to WGS on the HiSeq X Ten platform at Huada Gene, and obtained raw data (HiSeq X Ten: Q30 ≥ 75%, sequencing strategy: PE150)." (PMID 38678020, 2024). "In vitro, scratch and Transwell assays demonstrated that the migration and invasion abilities of LRP1–SNRNP25-overexpressing osteosarcoma cells were significantly increased." (PMID 38678020, 2024). "Next, to further demonstrate the regulation of 37LRP by pJNK in osteosarcoma cells, we treated LRP1–SNRNP25-overexpressing osteosarcoma cells with the pJNK inhibitor SP600125 (5, 10, and 15 μM) and treated the control group with the same concentration of DMSO." (PMID 38678020, 2024). "Our results open a new avenue for targeted therapy of patients with LRP1–SNRNP25-positive osteosarcoma." (PMID 38678020, 2024). "Our results provide the foundation for targeted therapy of patients with LRP1–SNRNP25 fusion-positive osteosarcoma." (PMID 38678020, 2024). "We sought to detect chimeric KCNMB4-CCND3 and LRP1-SNRNP25 protein products in 31 human osteosarcoma tissues by western blotting with antibodies against CCND3, KCNMB4, SNRNP25 and LRP1." (PMID 25300797, 2014). "LRP1–SNRNP25 is a potential therapeutic target for LRP1–SNRNP25-positive osteosarcoma." (PMID 38678020, 2024). "First, the frequency of LRP1–SNRNP25 fusion in patients with osteosarcoma is unknown, and more patients need to be enrolled in studies to determine this rate." (PMID 38678020, 2024). "The in vitro tracer system and endocytosis inhibitors demonstrated that there might be multiple pathways involved in their transport and that the LRP1-mediated endocytic pathway might be the main reason for the difference in cytotoxicity to osteosarcoma U2OS." (PMID 36356021, 2022). "In addition, transfection of LRP1-SNRNP25 into SAOS-2 human osteosarcoma cells showed that the expression of LRP1-SNRNP25 promotes SAOS-2 cell migration and invasion." (PMID 26738504, 2016). "LRP1-SNRNP25 expression was increased in both tumors via the LRP1 promoter activity of the fusion gene compared to the wild-type SNRNP25 expression in other osteosarcomas specimen." (PMID 26617523, 2015). "Two recurrent fusion genes associated with the 12q locus, LRP1-SNRNP25 and KCNMB4-CCND3, were identified and validated by RT-PCR, Sanger sequencing and fluorescence in situ hybridization, and were found to be osteosarcoma specific in a validation cohort of 240 other sarcomas." (PMID 25300797, 2014). "Expression of LRP1-SNRNP25 fusion gene promoted SAOS-2 osteosarcoma cell migration and invasion." (PMID 25300797, 2014). "Therefore, we hypothesized that in osteosarcoma cells, 37LRP might be involved in the processes of invasion and migration induced by the LRP1–SNRNP25 fusion." (PMID 38678020, 2024). "Therefore, pJNK and MMP2 may function as signaling molecules downstream of LRP1–SNRNP25 to influence the biological behavior of osteosarcoma cells." (PMID 38678020, 2024). "In previous experiments at the cellular level, LRP1–SNRNP25 overexpression was found to increase the invasion and migration of osteosarcoma cells." (PMID 38678020, 2024).